CLDN18 (claudin 18)
Diseases named in the same sentence as CLDN18 in open-access papers (continued):
Sharing a sentence is not in itself a finding about the gene and the disease.
Osteopenia (1 paper, 2014). Osteopenia is a term to define bone density that is not normal but also not as low as osteoporosis. "In this study, we examined if calcium deficiency caused by low‐gastric acidity was the cause of osteopenia phenotype observed in claudin‐18 (Cldn‐18) knockout (KO) mice." (PMID 24744879, 2014). "We have recently demonstrated that mice with disruption of claudin‐18 (Cldn‐18) gene exhibited osteopenia due to increased bone resorption (BR)." (PMID 24744879, 2014). "Comparison of the skeletal phenotype of high‐Ca Cldn‐18 KO and control mice revealed that an osteopenia phenotype seen at a normal‐Ca diet was still maintained at different skeletal sites in the KO mice till 10 weeks of age." (PMID 24744879, 2014). "As Cldn‐18 was globally disrupted and Cldn‐18 is expressed in other tissues, the purpose of this study was to investigate the possibility that the osteopenia phenotype of Cldn‐18 KO mice is mediated in part by disruption of Cldn‐18 in other tissues, that is, the stomach." (PMID 24744879, 2014). "Our findings that high‐calcium diet did not rescue the osteopenia phenotype in Cldn‐18 KO mice suggest that increased bone resorption is likely caused by direct effects of a lack of Cldn‐18 on osteoclasts rather than gastric pH changes." (PMID 24744879, 2014). "Importantly, the finding that the high dietary calcium did not rescue the osteopenia phenotype in Cldn‐18 KO mice supports the idea that low gastric acidity may not be responsible for the Cldn‐18 deficiency‐mediated bone loss." (PMID 24744879, 2014). "Collectively, our findings revealed that a high‐calcium diet failed to rescue an osteopenia phenotype in Cldn‐18 KO mice." (PMID 24744879, 2014). "Collectively, correction of serum calcium deficit did not correct decreased BMD and increased BR observed in Cldn‐18 KO mice, thus ruling out the possibility that gastric abnormalities contributed to the osteopenia phenotype in these mice." (PMID 24744879, 2014). "Third, we have not provided direct evidence using mice with conditional KO of Cldn‐18 in osteoclasts to rule out any role for Cldn‐18 expressed in the stomach for the osteopenia phenotype in Cldn‐18 KO mice." (PMID 24744879, 2014). "Based on these findings, we undertook studies to characterize the impact of a lack of Cldn‐18 on the gastric pH and serum calcium levels, and whether a dietary manipulation of calcium homeostasis can rescue the osteopenia phenotype in the Cldn‐18 KO mice." (PMID 24744879, 2014). "In addition, we found that a high‐calcium diet increased lumbar BMD and decreased BR in both Cldn‐18 KO and heterozygous control mice, whereas correcting the deficit in serum calcium in Cldn‐18 KO by feeding a high‐calcium diet did not correct the osteopenia phenotype and the increase in BR." (PMID 24744879, 2014).
pancreatic endocrine tumor (1 paper, 2023). "In contrast, among specific types of PCa, such as pancreatic neuroendocrine tumors, only 20% of the patients were positive for claudin-18.2, with a strong staining intensity in all the positive patients." (PMID 36959784, 2023). "Furthermore, SPT is positive for claudin-18.2and claudin-7 in a few cases, and pancreatic endocrine tumor (PET), acinar cell carcinoma(ACC), and pancreatoblastoma (PB) show strong expression of claudin-7 and a lack of claudin-5 expression." (PMID 36959784, 2023).
perihilar cholangiocarcinoma (1 paper, 2025). "Next, the presence of CLDN18 expression could be observed in 26.5% (n = nine of 34) of the perihilar cholangiocarcinoma (pCCA) subgroup, while 16.1% (n = five of 31) were positive in distal cholangiocarcinoma (dCCA)." (PMID 39731204, 2025).
Sepsis (1 paper, 2020). Sepsis is defined as life-threatening organ dysfunction caused by a dysregulated host response to infection. "In cultured alveolar epithelial cells isolated from rats, claudin-18 and occludin were significantly reduced during sepsis, whereas ZO-1 was not significantly affected." (PMID 32410859, 2020). "The expression of claudin-18 and occludin did not change during sepsis (data not shown) in left ventricular tissue." (PMID 32410859, 2020).
small bowel carcinoma (1 paper, 2025). "By finding retained CDH17 expression and frequent CLDN18 expression, our study indicates the possibility of widened treatment options in CD-associated small bowel carcinoma patients." (PMID 39164422, 2025). "The finding of frequent expression of CLDN18 in CD-associated small bowel carcinomas has implications for a targeted anti-claudin 18.2 antibody such as zolbetuximab therapy." (PMID 39164422, 2025).
squamous carcinoma (1 paper, 2022). "In ESCA, adenocarcinoma (mean TPM: 2569.9) expresses much higher CLDN18.2 than squamous carcinoma (mean TPM: 2.6)." (PMID 36922936, 2022).
tumor (127 papers, 2011 to 2026). "In mouse models, vaccination with Lv-CLDN18.2-DCs significantly suppressed tumor growth, which was associated with robust CD8+ T cell infiltration, reduced tumor cell proliferation (Ki-67), and decreased CLDN18.2-positive tumor cells in vivo." (PMID 41681913, 2026). "Because membranous CLDN18 staining has been associated in our cohort with more aggressive tumour biology, we investigated the impact of CLDN18 expression on survival." (PMID 39731204, 2025). "Beyond its role in tumor initiation, elevated CLDN18 expression is linked with advanced disease stage, including lymph node metastasis (LNM) and poorer OS in intrahepatic CCA." (PMID 41019366, 2025). "CT041 represents a second-generation CAR-T cell therapeutic agent engineered to specifically recognize the CLDN18.2 epitope, a tumor-associated antigen." (PMID 41019366, 2025). "Despite the possibility of statistical errors, a significant association was observed between tumor grade and CLDN18 expression." (PMID 37629433, 2023). "We found a significant association between CLDN18 expression and tumor differentiation, with well-differentiated tumors having a higher prevalence of CLDN18-positive cases." (PMID 37629433, 2023). "CLDN18 is also expressed in cancer tissues and has altered functions that are linked to tumour formation, proliferation, invasion and migration." (PMID 36969060, 2023). "A statistically significant association between CLDN18 immunoreactivity (≥1% of tumour cells) and lower pT stage was found (p=0.018)." (PMID 35925388, 2022). "The inhibiting event can be toxic, infectious, mutation of a tumor-suppressor gene in gastric progenitor cells, or deletion of a gene that is important in gastric barrier function, such as Claudin 18, or for mucosal protection, such as TFF1 or Muc5." (PMID 35426084, 2022). "High CLDN18 was associated with tumour site (antrum vs corpus), with a higher prevalence of positive cases among proximal (i.e. corpus) GCs (p = 0.016), whereas the distribution between GCs and GECs showed no statistically significance (29.7 vs 28.3%)." (PMID 31235864, 2019). "Which clinical or molecular subgroups benefit most from HIPEC is also unknown, partly because clinicians often lack data on key biomarkers (e.g., PD-L1 expression, tumor mutational burden, microsatellite stability, CLDN18.2 status)." (PMID 40994944, 2025). "Additionally, Q-1802 targets CLDN18.2 and PD-L1, which are associated with the potential to block immune checkpoints that closely impact tumor function." (PMID 40862764, 2025). "Furthermore, we validate that CLDN18 fusion mutations improve tumor response to paclitaxel treatment in GC with ovarian metastasis in vitro and vivo." (PMID 38704377, 2024). "In a retrospective study of a cohort of Italian patients using the same diagnostic antibody and criteria for CLDN18.2 positivity, a concordance rate of 81.5% was reported in pair-matched tumor samples from 27 patients collected from primary and metastatic sites." (PMID 38954176, 2024). "We examined the relationship between CLDN18 expression levels and MSI (Microsatellite Instability) and TMB (Tumor Mutation Burden) to determine if CLDN18 could serve as a predictive marker for the response to immunotherapy across various cancer types." (PMID 38774870, 2024). "In a retrospective study in a cohort of Japanese patients using the same diagnostic antibody and criteria for CLDN18.2 positivity, a concordance rate of 75.1% was reported between pair-matched tumor samples from 17 patients collected before and after 1L chemotherapy." (PMID 38954176, 2024). "Structure loss, which is one of the hallmarks of cancer, in the tumor gastric tissue may allow antibodies more accessible to CLDN18.2." (PMID 33755863, 2021). "Zolbetuximab was recently approved for the treatment of GC or GEJC with CLDN18.2 positivity (moderate to strong membranous CLDN18 expression in ≥ 75% of tumor cells) in Brazil." (PMID 41488290, 2026).
tumor (continued). "When using a CLDN18 positivity definition of moderate-to-strong membranous staining in ≥75% of tumor cells, as used in the SPOTLIGHT and GLOW trials, it was observed in 5.5% (13/237) of BTCs." (PMID 41374966, 2025). "One focus of our study was to determine the clinical relevance of the tumor heterogeneity of CLDN18.2 by comparing the CLDN18.2 status of primary tumors with their corresponding lymph node metastases using different methods." (PMID 40775258, 2025). "Using cutoff values of 40% and 25% for tumor areas with 2+/3+ IHC staining intensity, CLDN18.2 expression was observed in 65 (56.0%) and 69 patients (59.5%), respectively." (PMID 40749150, 2025). "Of patients with high CLDN18.2 expression (2+/3+ in 75% of tumor cells), ORR was 46.7% and 52.9%, and DCR was 93.3% and 88.2% at the same two dose levels." (PMID 40136475, 2025). "Ongoing phase III clinical trials are further evaluating its efficacy in patients with moderate-to-high CLDN18.2 expression, defined as >70% tumor cell positivity." (PMID 41019366, 2025). "CLDN18.2 positivity is defined as patients with ≥75% of tumor cells with moderate to strong membranous CLDN18 staining." (PMID 40136475, 2025). "As for Her2/neu or PD-L1, we can therefore state for CLDN18.2 as well that multiple tumor-bearing biopsies are necessary to obtain realistic results on the biomarker status." (PMID 40775258, 2025). "CAR-T therapies target tumor-associated antigens including KRAS G12D, mesothelin, EGFR, HER2, and CLDN18.2, with early trials reporting partial responses and stable disease." (PMID 40806185, 2025). "Patients with CLDN18.2-positive (defined as ≥75% of tumor cells showing moderate-to-strong membranous CLDN18 staining), HER2-negative, previously untreated, locally advanced unresectable or metastatic gastric or EGJ adenocarcinoma were included in the study." (PMID 41537121, 2025). "Overall, our results demonstrate that CAR-CLDN18.2 γδ T cells can effectively recognize CLDN18.2-positive target tumor cells and secrete high levels of Granzyme-B, Perforin-1, and IFN-γ to exert antitumor effects." (PMID 40149332, 2025). "A subgroup analysis revealed that patients with ≥70% tumor cells expressing CLDN18.2 had a higher ORR of 14%." (PMID 41374966, 2025). "Conversely, tumor-suppressive functions of CLDN18 have been observed in certain subtypes of gastric and lung cancers." (PMID 41019366, 2025). "Among patients with moderate-to-high CLDN18.2 expression (≥2+ in ≥50% tumor cells), the confirmed ORR was 23.0% (95% CI: 14.0–34.2)." (PMID 41374966, 2025). "Using the ssGSEA algorithm, analysis of CLDN18 expression and tumor-infiltrating immune cells based on GEO dataset GSE32225 revealed inverse correlations between CLDN18 expression and CD8+ TILs, which was consistent with outcomes using TIMER algorithm." (PMID 40951359, 2025). "To confirm the pathological identity of the GC tumor samples and validate tumor specificity, we also examined the expression of Claudin 18.2." (PMID 40992658, 2025). "The frequency of CLDN18.2 expression in malignant tumors varies depending on the tumor type, study methodology, and scoring criteria adopted." (PMID 40862764, 2025). "When both samples were compared, the lymph node metastasis displayed the CLDN18.2 expression of the tumor tissue of origin in 53/65 cases (81.5%)." (PMID 40775258, 2025). "Using different cutoff values, CLDN18.2-expressing tumor cells with 2+/3+ staining intensity in ≥40% and ≥25% of tumor cells were present in 70.6% and 73.5% of resected specimens, respectively." (PMID 40749150, 2025). "ORR was 37.5% and 44.8% in patients with moderate-to-high CLDN18.2 expression (2+/3+ IHC in ≥40% of tumor cells) at two different dose levels." (PMID 40136475, 2025). "Functionally, CLDN18 enhances the proliferative and invasive potential of CCA cells, supporting its role as a tumor-promoting factor and potential pathogenic driver." (PMID 41019366, 2025).
tumor (continued). "Early data suggest that AZD0901 is well tolerated and has promising anti-tumor activity in CLDN18.2-positive tumors." (PMID 41374966, 2025). "Substudy 3 will evaluate preliminary anti-tumor activity of AZD0901 monotherapy in patients with CLDN18.2-positive advanced or metastatic BTCs with ≤2 prior lines of therapy." (PMID 41374966, 2025). "In the dose-expansion phase, 52 patients with CLDN18.2-positive tumors (IHC ≥ 2+ in ≥50% of tumor cells) were enrolled." (PMID 41374966, 2025). "In the SPOTLIGHT study, patients were defined as CLDN18.2‐positive if ≥ 75% of tumour cells showed moderate‐to‐strong membranous CLDN18 staining using the VENTANA® CLDN18 (43‐14A) RxDx assay." (PMID 39731204, 2025). "The MONO trial was a phase II trial that assessed zolbetuximab monotherapy in 54 patients with recurrent or refractory advanced GC or lower esophageal adenocarcinoma (EAC) exhibiting moderate-to-strong CLDN18.2 expression in ≥50% of tumor cells." (PMID 41374966, 2025). "Patients with CLDN18.2-positive (1+/2+/3+ IHC in ≥1% of tumor cells) mG/GEJ cancer were divided into a subgroup of the study." (PMID 40136475, 2025). "The antibody recognizes a specific epitope located within the first extracellular loop of CLDN18.2, enabling selective tumor targeting with strong binding affinity." (PMID 41374966, 2025). "Positive CLDN18.2 expression was defined as ≥1+ membranous staining intensity in ≥10% of tumor cells." (PMID 41374966, 2025). "18% of the examined tumors showed a discordance between the CLDN18.2 expression in the primary tumor and the matched regional lymph node metastasis." (PMID 40775258, 2025). "Patients had to be CLDN18.2 positive, defined as IHC 2+/3+ in ≥50% of tumor cells, and to have been treated with two or more prior therapies." (PMID 40136475, 2025). "Tumour positivity for CLDN18.2 was determined as follows: ≥ 75% of tumour cells with moderate‐to‐strong CLDN18 membranous staining." (PMID 39731204, 2025). "HM2-CAR-T cells exhibited a stronger cytotoxicity against CLDN18.2-AsPCP-1 cells compared to other humanized VHH CAR-T cells, indicating HM2 was the most potent humanized VHH for engineering T cells to lyse CLDN18.2-positive tumor cells." (PMID 41550919, 2025). "Claudin-18 is highly expressed at tumor sites within the human body, whereas it is expressed at low levels or not at all in normal tissues, making it an ideal therapeutic target." (PMID 39813112, 2025). "Among the 32 (28%) patients who had a confirmed ORR across subgroups, 31 (97%) had CLDN18.2 membrane staining of at least 2+ intensity in at least 20% of tumor cells." (PMID 41374966, 2025). "Preclinical studies also indicate that osemitamab exposure can increase PD-L1 expression on CLDN18.2-positive tumor cells." (PMID 41374966, 2025). "This pivotal phase II trial evaluated satri-cel against treatment of physician’s choice (TPC) as third-line treatment in advanced GC/GEJC with CLDN18.2 positivity (defined as ≥2+ in ≥40% tumor cells on IHC)." (PMID 41374966, 2025). "What is important after identifying the correlation between the tumor microenvironment components and CLDN18.2 expression is the impact of that correlation on overall survival (OS)." (PMID 40647419, 2025). "A 2021 meta-analysis examined CLDN18.2 testing as a prognostic tool in GC with either any level of tumor cell 2+ to 3+ staining or a cutoff of ≥40% cell staining on IHC." (PMID 41374966, 2025). "First, a significant relationship was observed between CLDN18.2-positive GC and mid-to-upper third tumor locations in the stomach." (PMID 39306800, 2025). "Enhancing the affinity and specificity of CLDN18.2 monoclonal antibodies is critical for accurately differentiating between various CLDN18 subtypes within the complex tumor microenvironment." (PMID 40019387, 2025). "Little is known about its heterogeneity within the primary tumor and corresponding metastases and how many biopsies are needed to determine the true CLDN18.2 status of a tumor." (PMID 40775258, 2025).